SOST (sclerostin)
Diseases named in the same sentence as SOST in open-access papers (continued):
Sharing a sentence is not in itself a finding about the gene and the disease.
diabetes (continued). "Notably, combined diabetes mellitus and hypertension demonstrated substantial differences in results when changing the effect model, while age, hypertension, SOST, and FGF-23 showed consistent results across both models." (PMID 40314886, 2025). "Also, in the DN group, serum sclerostin level significantly positively correlated with the duration of diabetes, HbA1 C, and UACR, and CIMT (r = 0.678, 0.426, 0.798, 0.66, respectively, p < 0.005)." (PMID 40353858, 2025). "Moreover, elevated sclerostin levels have been consistently associated with vascular calcification, particularly in patients with chronic kidney disease (CKD) and diabetes, both of which are conditions that exacerbate cardiovascular risk." (PMID 39767786, 2024). "The role of SOST in obesity and diabetes is well documented." (PMID 38711986, 2024). "In conclusion, skin and serum AGEs are not independently associated with BMD, TBS, BTMs, and sclerostin in participants with relatively well-controlled T1D and participants without diabetes." (PMID 38505219, 2024). "In conclusion, the study confirms that circulating level of SOST is impacted by diabetes." (PMID 38711986, 2024). "Furthermore, consistent with previous studies, we found a significant positive correlation between serum sclerostin level and the duration of diabetes." (PMID 37919715, 2023). "In summary, vascular calcifications are very frequent among alcohol misusers, and are related to age, diabetes, hypertension, sclerostin, cholesterol, triglycerides and daily ethanol intake, and marginally, to obesity assessed by BMI in patients without ascites." (PMID 36895513, 2023). "Women with type 1 diabetes mellitus had higher circulating sclerostin levels compared to men." (PMID 36675692, 2022). "Within the present study we intended to assess potential determinants of low bone turnover in T2DM by evaluating the association between serum markers of bone resorption and formation with calciotropic hormones, serum sclerostin, glycaemic control and diabetes disease duration." (PMID 36190530, 2022). "Serum sclerostin might potentially be useful as a marker of decreased bone formation in premenopausal women with diabetes and therefore needs to be measured to prevent diabetoporosis in premenopausal women." (PMID 34690653, 2021). "A cross-sectional study was conducted to measure serum levels of IGF-1 and sclerostin in 40 premenopausal women with and without diabetes mellitus using an enzyme-linked immunosorbent assay." (PMID 34690653, 2021). "Sclerostin is highly expressed in cardiovascular disease, diabetes, and chronic kidney disease." (PMID 34976409, 2021). "In the present study, most of the participants had suffered from diabetes for more than 5 years, which might explain the high sclerostin serum levels." (PMID 34690653, 2021). "Since sclerostin influences the differentiation and maturation of osteoblasts, serum sclerostin might potentially be useful as a marker of decreased bone formation in premenopausal women with diabetes." (PMID 34690653, 2021). "Serum sclerostin levels can be related to age, BMI, bone density, kidney function, and diabetes." (PMID 32095286, 2020). "After adjustments for potential confounders, serum sclerostin levels present a negative association with muscle mass index (p < 0.001) and a positive association with diabetes (p=0.003)." (PMID 32095286, 2020). "Particularly, a cross-sectional study involving 46 patients aged 55 to 80 years (mean 71.1 ± 6.7 years, 36 men, 15 patients with type 2 diabetes mellitus) explored sclerostin production in atherosclerotic plaques of patients who underwent carotid endarterectomy." (PMID 32640551, 2020). "Thus, increased serum sclerostin levels were found in patients with chronic kidney disease, diabetes mellitus, prostate cancer, liver dysfunction and obesity." (PMID 33312059, 2020).
diabetes (continued). "PTHrP treatment improved acquisition of bone mass and strength in these mice, suggesting that using PTHrP to regulate sclerostin could be an important therapeutic strategy for maintaining bone health in diabetes." (PMID 31757981, 2019). "Intermittent PTH administration diminishes alveolar bone loss and sclerostin expression in osteocytes, but increases osteoid formation and mineralization, suggesting that intermittent PTH administration attenuates diabetes-aggravated alveolar bone loss by the induction of bone formation." (PMID 29544500, 2018). "Our results suggest that PTH may have an inhibitory effect on the induction of sclerostin expression in alveolar bone by diabetes similar to results seen in a study of estrogen-deprived rats treated with PTH." (PMID 29544500, 2018). "In addition, the IFX treatment induced high osteoid formation and low sclerostin-positive osteocytes in STZ-induced diabetes rats with periodontitis." (PMID 29240821, 2017). "Additionally, a recent clinical study shows that circulating sclerostin (an inhibitor of WNT signaling) is increased in type 2 diabetes mellitus patients." (PMID 26278788, 2015). "Since sclerostin is secreted by osteocytes, osteocyte may be a candidate for central role to bone homeostasis in diabetes." (PMID 23785354, 2013). "Notably, the m6A modification in SOST was markedly decreased in alveolar bone of diabetes." (PMID 37925419, 2023). "The serum sclerostin level increased in conjunction with a reduction of BMD in diabetes mellitus (DM) patients, and the values of sclerostin increased as renal function worsened." (PMID 35334561, 2022). "Considering that skeletal muscle mass is a predictor of mortality of patients, lean muscle mass was decreased in SOST-deficient mice, and a negative relationship of serum sclerostin and skeletal muscle mass was also reported in healthy subjects without diabetes." (PMID 31677125, 2020). "When we divided the entire cohort according to the presence of T2D, we found that the association between sex and sclerostin levels was stronger in the diabetes group compared to the group without diabetes (B = 17.17 [95% CI 6.40–27.93] p = 0.002 vs B = 9.80 [95% CI 1.36–18.24] p = 0.024)." (PMID 29928063, 2018). "Moreover, it is not clear if high circulating levels of sclerostin are a risk factor for mortality in the case of T2D patients and those without diabetes." (PMID 29928063, 2018). "However, whether TNF-α stimulates osteocytic RANKL and sclerostin expressions in diabetes with periodontitis is currently unclear." (PMID 29240821, 2017). "Thus, increased level of sclerostin as well as hyperglycemia, increased oxidative stress, and AGEs in diabetes may decrease osteocalcin production and accumulation." (PMID 23785354, 2013). "This study aimed to investigate the correlation between sclerostin and DKK1 levels and PAS in patients with type 2 diabetes mellitus (T2DM)." (PMID 42075515, 2026). "We found a positive correlation between the circulating sclerostin level and CVD-defining factors such as age (r = 0.193; p = 0.024) and duration of diabetes (r = 0.275; p < 0.001)." (PMID 37919715, 2023). "We performed a multivariate logistic regression analysis including age, hypertension, diabetes mellitus, dialysis duration, MAP, hs-CRP, ALP, phosphate, sclerostin, and miRNA-29b." (PMID 34976409, 2021). "However, the regulation of PTH on sclerostin may be impaired in diabetes." (PMID 32851096, 2020). "Age, weight, diabetes, osteocalcin levels, and intact PTH levels had marginally statistical significance (P > 0.05) or marginal effects (OR = ~ 1) on sclerostin levels." (PMID 31315601, 2019). "Based on univariate analysis, age, albumin, uric acid, sclerostin, CIMT, diabetes and history of cardiovascular disease (p < 0.05) were included." (PMID 30314461, 2018). "Circulating sclerostin is also increased in T2DM patients with atherosclerotic lesions, suggesting a connection with macrovascular complications of diabetes." (PMID 30192850, 2018).
diabetes (continued). "Since sclerostin and DKK1 levels are significantly elevated in diabetes and Wnt pathways also participate in glucose metabolism and T2DM development, recent studies have begun to focus on whether these antibodies also exert an effect on glucose homeostasis." (PMID 40149867, 2025). "After adjusting for BMI, fasting glucose levels, diabetes, smoking, and CRP levels, independent of other cardiovascular risk factors, every 1 pmol/L increase in sclerostin levels was associated with a 5.4% increase in the risk of developing PAD." (PMID 40731833, 2025). "In conclusion, we did not identify significant associations between either skin or serum AGEs and BMD, TBS, BTMs, and sclerostin in people with relatively well-controlled T1D and people without diabetes." (PMID 38505219, 2024). "Patients with diabetes (Z = 2.10; p = 0.035) or hypertension (Z = 2.65; p = 0.008) showed higher sclerostin levels than patients without diabetes or hypertension." (PMID 36895513, 2023). "It was reported that the alterations in microarchitecture and bone turnover associated with type 2 diabetes are not a consequence of the elevated expression of sclerostin in an animal model of diabetes." (PMID 35216490, 2022). "Sclerostin levels increase with age and PTH was shown to be an independent determinant of sclerostin in patients without diabetes." (PMID 36190530, 2022). "The levels of sclerostin were significantly higher in premenopausal women with diabetes mellitus than in the non-diabetic group." (PMID 34690653, 2021). "We compared the levels of IGF-1 and sclerostin in premenopausal women with and without diabetes as potential markers of diabetoporosis in premenopausal women with diabetes." (PMID 34690653, 2021). "Subjects with VC were more likely to be male and have diabetes, and had significantly higher sclerostin and osteoprotegerin circulating levels than those without VC." (PMID 34644326, 2021). "Our data indicate that premenopausal women with diabetes have significantly higher serum levels of sclerostin than the non-diabetic group." (PMID 34690653, 2021). "Our patients with diabetes showed higher sclerostin concentrations than non-diabetic patients and significantly higher values for adiposity measures such as BMI, WC, and HC." (PMID 32095286, 2020). "A study of diabetics undergoing hemodialysis presents high levels of sclerostin compared to those without diabetes." (PMID 32095286, 2020). "In this study population, the prevalence of diabetes (24% of the patients in the low and 16% of the patients in the high skeletal sclerostin expression group) was not significantly different (p = 0.4052) between both groups." (PMID 31756992, 2019). "High BMD, old age, male sex, increased weight and height, diabetes, and high osteocalcin and uric acid levels were observed in patients with high serum sclerostin levels and an inverse relation was noticed between PTH and sclerostin." (PMID 31315601, 2019). "In studies mainly on non-CKD population, sclerostin levels were correlated positively with age, male sex, diabetes, and bone mineral density (BMD) but inversely with physical activity and parathyroid hormone (PTH) levels." (PMID 31315601, 2019). "Sclerostin levels between the patients with and without diabetes were comparable (174.24 vs. 160.33 pmol/L; median, p = 0.718)." (PMID 30314461, 2018). "In this study, the sclerostin levels were not measured during the follow-up, and the self-reported diagnosis of diabetes had relatively low sensitivity (77.8%), both of which may lead to the underestimation of diabetes incidence." (PMID 40149867, 2025). "Based on the multivariate analysis, sclerostin was an independent predictor of PAD (odds ratio: 1.054 per 1 pmol/L increase, 95% confidence interval: 1.019–1.090, p = 0.002) after adjusting for body mass index, fasting glucose levels, diabetes, smoking, and CRP levels." (PMID 40731833, 2025).
diabetes (continued). "Nevertheless, PTH and both doses of ABL decreased bone mRNA Sost expression and ABL also reduced circulating sclerostin protein levels, suggesting a potential role of Sost/sclerostin downregulation in the anabolic function of the PTH1R ligands in the context of diabetes." (PMID 37076478, 2023). "Hence, the goal of this study was to see if there was any link between sclerostin, glycaemic parameters, and insulin resistance/sensitivity in Indian individuals with diabetes and prediabetes, which was not addressed before." (PMID 36004027, 2022). "This study was conducted to compare the levels of IGF-1 and sclerostin in premenopausal women with and without diabetes, as they might be useful as markers of decreased bone formation in premenopausal women with type 2 diabetes." (PMID 34690653, 2021). "Regarding patients with diabetes not on dialysis, other studies have shown increased sclerostin in comparison to the non-diabetic population, and this may explain, at least in part, the mechanisms underlying bone fragility in diabetics." (PMID 32095286, 2020). "However, duration of diabetes was not an independent factor for circulating sclerostin in multiple regression analysis (β = −0.069, P = 0.372)." (PMID 25053944, 2014). "Sclerostin was identified in the plaques of all the patients, and its levels were significantly higher in the media compared with the intima, as well as higher in VSMCs compared with infiltrating macrophages, irrespective of history of type 2 diabetes mellitus." (PMID 32640551, 2020). "In type 1 diabetes (T1DM) and T2DM sclerostin levels were found to be higher compared to non-diabetic controls which might be due to an impaired suppression of sclerostin production by PTH in patients with diabetes." (PMID 36190530, 2022).
van Buchem disease (91 papers, 2009 to 2025). "SOST is a gene that encodes Sclerostin and Sclerostin is an endogenous inhibitor of Wnt and was identified in another rare human diseases, sclerosis and Van Buchem disease." (PMID 38199244, 2024). "The ECR5 region is deleted in patients with van Buchem disease, and its deletion in mice causes a drastic decrease in SOST levels in osteocytes." (PMID 35052478, 2022). "In a patient with Van Buchem disease, the administration of glucocorticoids halted new bone formation, suggesting that glucocorticoids restrain bone formation due to sclerostin deficiency in humans." (PMID 35160258, 2022). "ECR5 is deleted in patients with Van Buchem’s disease, and its deletion in mice causes a drastic decrease in sclerostin levels in osteocytes." (PMID 33419004, 2021). "Mutations in SOST (sclerostosis and van Buchem’s disease) cause enhanced bone formation, higher bone mineral density, and calvaria overgrowth, which frequently compresses cranial nerves leading to hearing loss." (PMID 33326993, 2021). "Loss-of-function mutations in the SOST gene (encoding sclerostin) cause osteosclerosis and van Buchem disease with abnormally high bone mass, suggesting that bone formation is usually suppressed by sclerostin through the inhibition of Wnt/β-catenin signals." (PMID 32050469, 2020). "Human mutations in the Wnt antagonist Sclerostin (SOST) also cause high bone mass through loss of pathway inhibition (Van Buchem disease OMIM 239100 or Sclerostosis OMIM 269500)." (PMID 25299576, 2014). "Partial deletion of a regulatory region approximately 35 kb distal to the SOST gene is causative of the high bone mass phenotype seen in Van Buchem's disease." (PMID 21991382, 2011). "A deletion downstream of the SOST gene, which results in reduced sclerostin expression, is associated with a milder form of the disease called van Buchem disease." (PMID 20981340, 2010). "Loss-of-function (LoF) SOST variants cause sclerosteosis, a rare condition of excessive bone overgrowth; a 52-kb deletion located approximately 35-kb downstream of SOST is thought responsible for the milder phenotype of van Buchem’s disease." (PMID 34539568, 2021). "The remaining patients are homozygous carriers of 52 kb deletion downstream of SOST, which removes a specific regulatory element, reduces the protein expression, and determines the phenotype known as Van Buchem Disease (VBD)." (PMID 40943101, 2025). "Human mutations in LRP5 and SOST (sclerostin) alter WNT signaling and cause osteoporosis-pseudoglioma syndrome (OPPG) and van Buchem disease." (PMID 36814601, 2023). "Clear illustrative examples of this are sclerosteosis and van Buchem disease, two related conditions arising from mutations affecting the SOST gene which codes the protein sclerostin." (PMID 34539568, 2021). "Van Buchem’s disease (MIM 239100), a third sclerostin clinical entity, is caused by a 52-kb deletion of a regulatory region located 32 kb downstream of SOST and necessary for the correct expression of the gene." (PMID 33419004, 2021). "Defects in the SOST gene were described as early as in the 1950s,: Van Buchem disease or “hyperostosis corticalis generalisata familiaris” is caused by deletion of an element of the SOST gene." (PMID 31858345, 2020). "A similar disease, endosteal hyperostosis (van Buchem disease: OMIM: 239100), is associated with a deletion of 52 kbps downstream of the SOST gene (evolutionarily conserved region; ECR), leading to an increase in bone mass." (PMID 31698687, 2019). "Further evidence comes from Van Buchem Disease, which is characterized by a noncoding deletion which removes a SOST-specific regulator (Sebastian & Loots, 2018;Yavropoulouet al., 2014)." (PMID 31031968, 2019). "The diagnosis of van Buchem disease was confirmed by the finding of a 52-kb homozygous deletion 35 kb downstream of the SOST gene on chromosome 17q12-q21." (PMID 26892377, 2016).
van Buchem disease (continued). "Van Buchem's disease is a similar disorder with generalized hyperostosis and a 52-kb deletion downstream (35 kb) of the SOST gene that removes a SOST-specific regulatory element." (PMID 19936252, 2009). "The regulation of Sost transcription and sclerostin synthesis is complex and has been intensely investigated since the identification of the Sost gene through genetic linkage analysis in patients with sclerosteosis and van Buchem disease." (PMID 39171525, 2024). "Failure of this mechanism is the cause of Van Buchem’s disease or hyperostosis corticalis generalisata, where the absence of sclerostin results in uncontrolled bone formation." (PMID 35160258, 2022). "Furthermore, a 52 kb deletion of a region downstream of the gene, necessary for the correct expression of SOST, has also been found in patients with van Buchem disease." (PMID 35052478, 2022). "In patients with van Buchem disease, there were no mutations in the SOST gene but a 52-kb homozygous noncoding deletion 35 kb downstream of the SOST gene was identified." (PMID 26892377, 2016). "In the related van Buchem disease, an enhancer element for SOST expression is silenced." (PMID 27558933, 2016). "Furthermore, it became clear that modulation of sclerostin concentration and activity affects bone mass, as indicated by the fact that SOST SNVs are associated with BMD and that heterozygous carriers for mutations causing sclerosteosis and van Buchem disease also show an increased bone mass." (PMID 34539568, 2021). "In a few bone biopsies from patients with van Buchem disease increased bone formation was documented and lack of sclerostin expression in osteocytes." (PMID 26892377, 2016).